NSUN2 (NOP2/Sun RNA methyltransferase 2)
Diseases named in the same sentence as NSUN2 in open-access papers (continued):
Sharing a sentence is not in itself a finding about the gene and the disease.
tumor (continued). "The results showed that NSUN2 was mainly expressed in the nucleus of NPC cells, which is consistent with the localization of NSUN2 in other tumor cells." (PMID 35574373, 2022). "In 52 paired PCa and adjacent normal tissues, NSUN2 mRNA expression levels were markedly elevated in tumour tissues (p < .01)." (PMID 36169095, 2022). "NSUN2, NSUN5, NSUN6, DNMT3A, DNMT3B, ALYREF, and TET3 acted as tumor risk factors, and overexpression of these genes led to a poorer prognosis for ccRCC patients." (PMID 36661693, 2022). "The first study showed that NSUN2 was involved in how lncRNA NMR promotes tumor progression in ESCC." (PMID 35484099, 2022). "This idea was verified in vitro experiments, where NSUN2 deletion increased the sensitivity of tumor cells to the anticancer drugs 5-fluorouracil and cisplatin in a mouse tumor model." (PMID 36437944, 2022). "In the NSUN2 OE group, the tumour volume was significantly increased, while in the NSUN2 knockdown group, the tumour volume was significantly decreased." (PMID 36169095, 2022). "Decreased tumour volume and weight were observed in the NSUN2 shRNA group, and increased tumour size was observed in the NSUN2 OE group compared with the control group." (PMID 36169095, 2022). "Chromatin immunoprecipitation sequencing (ChIP‐seq) profiling of AR genome‐wide binding sites demonstrated that the NSUN2 promoter region has significant AR binding signals in both PCa cell lines and tumour samples." (PMID 36169095, 2022). "YBX1 and ALYREF, discovered by Yang, are the only known m5C 'readers.'17, 18 NSUN2 has been reported to be involved in promoting the progression of some tumours." (PMID 36169095, 2022). "Although the functional role of RNA cytosine-5 methylation is not fully understood in cancer development, expression of NSUN2 is elevated in tumors of multiple tissue origin suggesting a fundamental link to tumor progression." (PMID 34414180, 2021). "Taken together, NSUN2 is a notable biomarker for predicting tumor metastasis and the prognosis and a promising therapeutic target in clinic applications." (PMID 34512153, 2021). "Very recently NSUN2 was also shown to promote tumour progression by methylation of NMR ncRNA in oesophageal cancer." (PMID 33461542, 2021). "Up to 3 weeks after injection, we found that stable knockdown of NSUN2 suppressed tumor growth in nude mice effectively." (PMID 32332707, 2020). "As cell proliferation plays an important role in tumor development, we selected cell cycle related pathways as a candidate targets of NSUN2 for further study." (PMID 32332707, 2020). "The average tumor weight and volume of NSUN2 knockdown cells group were also significantly lower than those in the wild-type group." (PMID 32332707, 2020). "NSun2 is highly expressed in head and neck squamous carcinoma, and the patients with high levels of NSun2 in tumor tissue have a shorter survival time." (PMID 33093178, 2020). "NSUN2 intensity in all groups was analyzed by Image J software, which also showed that NSUN2 protein expression was shown to be significantly increased in tumor stages I-IV (stage I, P=0.04; stage II, P=0.005; stage III, P=0.017; stage IV, P=0.005)." (PMID 27447970, 2017). "Ki-67 expression was shown to correlate with NSUN2 expression (P<0.001), which agrees with previous studies showing that Ki-67 index correlates with the tumor grade and clinical behavior of cancer." (PMID 27447970, 2017). "The analysis of double knockout Dnmt2/NSun2 mice and the deletion of NSun2 in a tumour mouse model suggested a role of 5-methylcytosine in the regulation of global protein synthesis and cell fate." (PMID 27974624, 2016).
tumor (continued). "Moreover, the overexpression of wild-type NSUN2 leads to gefitinib resistance and tumour recurrence, which are related to the m5C site at the CDS region of QSOX1 mRNA." (PMID 40860147, 2025). "Moreover, NSUN2 modulates ferroptosis, glucose metabolic competitiveness, and drug resistance, further promoting tumor proliferation, invasion, and therapy resistance." (PMID 41256859, 2025). "Across multiple tumor types, NSUN2 acts as a positive regulator of tumor progression by stabilizing target RNAs through m5C methylation, enhancing RNA stability, translation efficiency, and splicing, and activating oncogenic signaling pathways (e.g., Ras/PI3K–AKT/ERK, β-catenin, STAT3)." (PMID 41256859, 2025). "For example, the m5C methyltransferase NSUN2 initiates a positive feedback loop in CRC, modifying ENO1 mRNA to boost lactate production, which in turn enhances NSUN2 expression and activity through lactylation, ultimately driving metabolic reprogramming and tumor progression." (PMID 41361128, 2025). "Building on the glucose-competition/NSUN2 axis's role in enhancing the nutrient acquisition advantage of tumor cells, we explored whether this mechanism could influence HCC evolutionary fate and contribute to CD8+ T cell functional activity within the TIME." (PMID 40765828, 2025). "In summary, NSUN2 exerts a central role in tumor metabolic reprogramming via RNA m5C modification." (PMID 41256859, 2025). "Further analysis indicates that NSUN2 negatively regulates immune cell infiltration in the NPC tumor microenvironment (TME), suggesting that its expression level may be inversely correlated with sensitivity to immunotherapy and chemotherapy." (PMID 41256859, 2025). "NSUN2 was markedly elevated in tumor tissues compared with nearby control tissues." (PMID 41436732, 2025). "Furthermore, a potential synergistic effect between Nsun2-i4 and PD-1 was observed, with the combination showing a significantly enhanced inhibitory effect on tumor growth compared to individual treatments." (PMID 41413017, 2025). "Moreover, IHC staining confirmed that overexpression of NSUN2 significantly upregulated Ki‐67 expression in the xenograft tumour tissues." (PMID 40156167, 2025). "In summary, NSUN2 exerts a central role in tumor cell proliferation, metastasis, metabolic reprogramming, and therapy resistance through both m5C-dependent and -independent mechanisms, functioning as a critical oncogenic factor in multiple cancers and representing a potential therapeutic target." (PMID 41256859, 2025). "Based on these findings, we have proposed that tumor cells could boost their glucose metabolism activity via the glucose-competition/NSUN2 axis, consequently hindering the metabolism and anti-tumor capabilities of CD8+ T cells." (PMID 40765828, 2025). "In the tumor context, NSUN2 also exhibits significant immunoregulatory functions." (PMID 41256859, 2025). "Furthermore, in certain tumor types, NSUN2-mediated m5C modification can indirectly modulate T cell infiltration and antitumor immune responses through the regulation of metabolic reprogramming pathways, including glycolysis and lipid metabolism." (PMID 41256859, 2025). "Silencing NSUN2 in AML mice reduced the tumor burden and prolonged survival." (PMID 41462962, 2025). "Moreover, NSUN2 expression levels vary among different tumor types and individual patients, necessitating biomarker-guided patient stratification and treatment optimization in accordance with the characteristics of the tumor microenvironment." (PMID 41256859, 2025). "Notably, the regulatory effect of glucose on NSUN2 expression and its downstream modulation of glycolytic enzymes, initially observed in vitro, was further validated in tumor tissues." (PMID 40765828, 2025). "Collectively, NSUN2 links immune cell function with tumor glycolytic metabolism and immune evasion." (PMID 41256859, 2025).
tumor (continued). "Similarly, tumor-derived lactate induces NSUN2 lactylation at K356, increasing its binding ability to specific m5C-modified RNAs and driving m5C-dependent metabolic reprogramming to support CRC invasion and metastasis." (PMID 40859309, 2025). "Conversely, NSUN2 overexpression promotes tumor growth and metastasis." (PMID 41256859, 2025). "Notably, this process involves a positive feedback loop initiated by glucose uptake in tumor cells, which upregulates NSUN2 expression." (PMID 40765828, 2025). "Furthermore, the NSUN2-mediated GLUT1 stabilization via m5C modification enhances the competitive advantage of tumor cells in glucose acquisition, accelerating malignancy in HCC." (PMID 41373022, 2025). "NSUN2, the methyltransferase that catalyzes m5C modification, has been reported to exert its biological functions primarily in an m5C‐dependent manner, such as epidermal stem cell self‐renewal, tumour cell stemness and tumourigenesis." (PMID 40156167, 2025). "Furthermore, the NSUN2 inhibitor, Nsun2-i4, has demonstrated efficacy in significantly curbing tumor growth and reducing tumor burden in CRC." (PMID 40114967, 2025). "In liver and gallbladder tumors, NSUN2 promotes tumor progression through multiple pathways." (PMID 41462962, 2025). "However, how NSUN2 activity is response to acidic condition in tumor microenvironment and then regulates cancer cell survival remain to be clarified." (PMID 39742570, 2025). "Moreover, in vivo experiments demonstrated that SRSF6 overexpression reversed the enhanced drug sensitivity observed in NSUN2-knockout cells, leading to tumor growth and final tumor weights comparable to those of NSUN2-knockout controls." (PMID 40083919, 2025). "Furthermore, the extracellular vesicle NSUN2 derived from DLBCL cells promoted tumor growth by positively regulating PDL1, stabilizing it in a YBX1-dependent manner, promoting tumor immune escape and M2 macrophage polarization." (PMID 41462962, 2025). "However, all current BCa studies examined the NSUN2 expression in whole tumor tissue, including tumor cells and immune cells." (PMID 41354740, 2025). "Furthermore, NSUN2 expression can be assessed through histological analysis or RNA sequencing, providing valuable information for tumor diagnosis, prognostic evaluation, and therapeutic response prediction." (PMID 41256859, 2025). "Elucidating key modification sites on NSUN2 and targeting these sites may enable novel drug development strategies, such as PROTACs or molecular glues, ultimately improving tumor prognosis." (PMID 41413017, 2025). "Notably, treatment with an autophagy inhibitor (3-MA) or a ferroptosis inhibitor (Fer-1) partially restored tumor growth in NSUN2-knockdown cells, validating the critical role of autophagy and ferroptosis in NSUN2-mediated OSCC progression." (PMID 41436732, 2025). "Functionally, NSUN2 overexpression significantly promotes cell proliferation, migration, and invasion In vivo experiments reveal that tumor growth and lung metastasis are markedly suppressed in NSUN2 knockout mice." (PMID 40114967, 2025). "NSUN2 plays a pivotal role in the development and progression of various cancers by regulating gene expression and enhancing mRNA stability, serving as a key hub connecting m5C modification with tumor malignancy phenotype." (PMID 41256854, 2025). "Therefore, it is important to explore the m5C‐independent functions of NSUN2 in tumour progression, with the aim of identifying targeted therapeutic approaches for the treatment of CRC that focus on NSUN2 as a potential therapeutic target." (PMID 40156167, 2025).
tumor (continued). "In accordance with in vitro results, subcutaneous tumor, tail vein injection lung metastasis, and intra‐spleen injection liver metastasis models were established, and the results indicated that NSUN2 knockout significantly inhibited subcutaneous tumor growth and distant metastasis." (PMID 38769664, 2024). "NSUN2 protein expression also showed a positive correlation with the NSCLC tumor stage." (PMID 38403250, 2024). "As the main methyltransferase, NSUN2 plays a crucial regulatory role across diverse tumor types." (PMID 38844963, 2024). "Likewise, substantially elevated expression levels of the NSUN2 protein were observed in tumor tissues of azoxymethane/dextran sulfate sodium (AOM/DSS)‐ and DSS (APCMin/+/DSS)‐induced CRC mouse models compared with those of normal colorectal tissues." (PMID 38769664, 2024). "We then explored the effects of NSUN2 knockdown on tumor growth and metastasis in vivo." (PMID 38566431, 2024). "Furthermore, as adverse prognosis is often attributed to tumor metastasis, we conducted Transwell and wound healing experiments and revealed that NSUN2 knockdown significantly inhibited the migration and invasion activity of SCC25 and HSC3 cells." (PMID 39595099, 2024). "What’s more, the TUNEL staining results showed that NSUN2 could significantly decrease the apoptotic levels of xenograft tumor tissues; silencing NFE2L2 substantiality reversed this effect." (PMID 38403250, 2024). "To further determine whether NSUN2 functions as a tumor‐promoting factor in CRC, we constructed two NSUN2‐knockout (NSUN2KO or NSUN2−/−) CRC cell lines using the CRISPR/ Cas9 gene editing system." (PMID 38769664, 2024). "Compared to control adjacent tissues, NSUN2 was significantly upregulated in tumor tissues." (PMID 39595099, 2024). "The results showed that treatment with either compound alone effectively reduced subcutaneous tumor growth; however, co‐administration of PD‐1 with Nsun2‐i4 in combination demonstrated a significantly enhanced inhibitory effect on tumor growth compared with individual treatments." (PMID 38769664, 2024). "Compared with the control group, the NSUN2 knockdown group showed significantly decreased tumour sizes and weights, which could be rescued by reintroducing NSUN2." (PMID 38468490, 2024). "To this end, after NSUN2 expression levels were measured, we implanted fresh primary tumour samples resected from CRC patients into immunocompromised mice and then intraperitoneally injected PBS or verteporfin, a disruptor of YAP/TAZ‐TEAD‐mediated transcription." (PMID 38468490, 2024). "In addition, the tumor formation assay revealed that knockout of NSUN2 remarkably suppressed sphere formation and cancer stemness in CRC cells." (PMID 38769664, 2024). "The results showed that tumour tissues with high NSUN2 expression had higher levels of SKIL." (PMID 38468490, 2024). "As expected, Nsun2‐/‐ mice developed smaller and fewer tumours than Nsun2+/+ mice." (PMID 38468490, 2024). "In addition, the expression of NSUN2 was highly associated with different immune subtypes, such as LIHC and LUAD tumor types." (PMID 37769000, 2023). "Functional experiments showed that NSUN2 could accelerate PC proliferation and promote migration and invasion in vitro, thereby enhancing tumor growth and metastasis in vivo." (PMID 37393317, 2023). "Therefore, in future work, more experiments need to be performed to verify the expression profiles and functions of NSUN2 in tumor progression and immune therapy." (PMID 37769000, 2023). "In addition, because the checkpoint PD-L1 plays an important role in tumor escape, we further overexpressed NSUN2 and found that NSUN2 increased the protein expression of PD-L1." (PMID 37769000, 2023). "Moreover, NSUN2 was found to confer resistance to chemotherapy drugs in ATC, suggesting that NSUN2 regulates a tumour progression network." (PMID 37983928, 2023).
tumor (continued). "Moreover, we analyzed the expression of NSUN2 in the pathological tissues of different tumor types using the immunohistochemistry (IHC) images provided by the HPA database." (PMID 37769000, 2023). "Furthermore, the relationships between NSUN2 and immune cells in three tumor types were further analyzed by the TIMER database, and we found that NSUN2 was associated with the infiltration levels of immune cells such as DCs, neutrophils and CD8 T cells." (PMID 37769000, 2023). "Depletion of NSUN2 significantly inhibited cell growth and metastasis, whereas ectopic expression of LRRC8A in NSUN2-depleted cells could largely rescue the tumor-suppressive effect of NSUN2 knockdown." (PMID 36632452, 2023). "Importantly, NSUN2‐mediated m5C modification is involved in cell proliferation and invasion in a variety of tumours, by activating oncogenes or inhibiting tumour suppressors." (PMID 37228185, 2023). "NSUN2 was found to be highly expressed in most tumor types compared with normal tissues and presented an increasing expression trend with increasing tumor stage in some tumor types." (PMID 37769000, 2023). "Moreover, the TISIDB, TIMER2.0 and Sangerbox platform were used to depict the relationships between NSUN2 and immune molecular subtypes, tumor-infiltrating lymphocytes (TILs), immune checkpoints (ICPs) and immunoregulatory genes." (PMID 37769000, 2023). "Among them, DNMT3b, DNMT1, ALYREF, TET2, NSUN2 and NSUN5 mutations imply that m5C may act abnormally in the tumour." (PMID 37408139, 2023). "Therefore, we further explored the relationships between the expression of NSUN2 and immune and molecular subtypes in different tumor types." (PMID 37769000, 2023). "The results revealed that NSUN2 might have an important function in tumor progression by participating in the immune response." (PMID 37769000, 2023). "Results demonstrated that NSUN2 played a tumor-promoting role in CC." (PMID 36632452, 2023). "In our study, NSUN2 was also significantly overexpressed in other tumor types." (PMID 37769000, 2023). "Besides, NSUN2 has a dual role in tumor cells, playing different functions at different stages of the cell cycle in animal tissues." (PMID 36335189, 2022). "However, the functional roles, overexpression mechanisms of NSUN2 and its relation between clinicopathological characteristics of tumor are still obscure." (PMID 36118897, 2022). "As a new epigenetic regulation mechanism in tumour biology, whether or how NSUN2 plays roles in PCa, even in CRPC and drug resistance remains largely unknown." (PMID 36169095, 2022). "NSUN2 promotes tumor progression through both m5C-dependent and -independent pathways." (PMID 35562754, 2022). "Autotaxin mRNA can be methylated by NSUN2 and promote tumour migration and invasion." (PMID 36169095, 2022). "Subcutaneous models further uncovered the role of NSUN2 in tumor growth." (PMID 36169095, 2022). "NSUN2 is highly expressed in U87 and regulates the migration ability of tumor cells." (PMID 36203569, 2022). "In addition, we also analyzed the expression of NSUN members in GSE46602, NOP2 and NSUN2 were highly expressed in tumor tissues, and NSUN4 was lowly expressed." (PMID 35978830, 2022). "To determine whether our two prognosis-related genes can reflect the status of tumor immune infiltration, we further used the Timer database to analyze the correlation of NSUN2 and NSUN6 with immune cell infiltration in TCGA." (PMID 33928086, 2021). "Similar to MYC, NSUN2 was also highly expressed in various tumours." (PMID 34638933, 2021). "We thus hypothesized that NSUN2-mediated m5C hypermethylation might promote ESCC tumor progression mainly by regulating PI3K/AKT and ERK/MAPK signaling." (PMID 34345012, 2021). "NSUN2 promoted the progression and metastasis of tumor cells in vitro." (PMID 34504059, 2021). "Consistently, NSUN2 protein levels were also significantly correlated with tumor stages." (PMID 34345012, 2021).